EGFR (epidermal growth factor receptor)
Diseases named in the same sentence as EGFR in open-access papers (continued):
Sharing a sentence is not in itself a finding about the gene and the disease.
cancer (continued). "TangomiRs were developed by EnGeneIC to deliver miR16 mimics encapsulated in TargomiRs composed of bacterial minicells with an anti-EGFR bispecific antibody to target EGFR-expressing cancer cells." (PMID 38338746, 2024). "The EGFR inhibitors gefitinib and erlotinib were developed on the assumption that many cancers overexpress this receptor." (PMID 38612902, 2024). "It has been previously shown that faster EGFR recycling to the membrane enables the cancer cell to sustain PI3K/Akt activation and cancer progression, which is in agreement with our findings in LUSC cells." (PMID 39443476, 2024). "Gefitinib is an inhibitor of the EGFR tyrosine kinase domain and effectively suppresses cancer cell proliferation by downregulating EGFR signaling, particularly within TNBC." (PMID 38476263, 2024). "Because of the extensive clinical application of EGFR inhibitors in cancer patients, their toxicity and pharmacokinetics are well known." (PMID 39653700, 2024). "Previous reports have shown that EGFR activation mediates actin dynamics via RhoA signaling in various cancers." (PMID 39742082, 2024). "Exosomal proteins such as HSP70 and EGFR are involved in cancer cell migration, invasion and drug resistance, and can be used as potential biomarkers for diagnosis and targeted drug delivery." (PMID 39497820, 2024). "The evasion of EGFR inhibitor-induced apoptosis as a mechanism of resistance has also been validated in patient-derived MGH134 resistant cells by scientists from MGH Cancer Center." (PMID 39543744, 2024). "Results showed that American Joint Committee on Cancer staging, the use of EGFR inhibitor, age, T‐staging, and lymphovascular invasion were the five input features contributing the most to the model algorithm." (PMID 39556481, 2024). "As for its effectiveness, Osimertinib is considered the first-line therapy for untreated EGFR mutation-positive advanced NSCLC and is well tolerated by cancer patients." (PMID 38391832, 2024). "Anti-FGFR (fibroblast growth factor receptor) is a prime targeting agent for therapeutic intervention in cancers where it is dysregulated, often due to overactive EGFR signaling." (PMID 39525484, 2024). "Overall, these findings highlight the potential of kaempferol as a therapeutic agent targeting glycolysis in cancer cells, with EGFR serving as a key molecular target for its anticancer effects." (PMID 38730663, 2024). "This was also the case when treating mixed cultures of EGFR- and ErbB2-expressing cancer cells that served as a model for heterogeneous target antigen expression, which is often observed in solid tumors and can contribute to their escape from immunotherapy." (PMID 38334638, 2024). "COX-2 and EGFR are promising pharmacological and chemopreventive targets for treating various pathological conditions, including cancer." (PMID 38248333, 2024). "Through cell cycle dysregulation and increased cancer cell survival, the interaction of EGFR with TGFα and EGF promotes tumorigenesis." (PMID 39590368, 2024). "The role of the epidermal growth factor receptor (EGFR) family in cancer has been extensively investigated." (PMID 39456984, 2024). "Whereas, little is known about the role of tubulin detyrosination in EGFR endosomal trafficking or downstream signal transduction in cancers." (PMID 39443476, 2024). "EGFR plays an important role in signalling pathways critical to cancer progression, including Ras/Raf/MEK/ERK and PI3K/AKT/mTOR." (PMID 39518152, 2024). "EGFR belongs to a family of transmembrane glycoproteins with similar structures and signaling pathways, whose interactions significantly influence cancer cell activity." (PMID 39768978, 2024). "Cetuximab has been successfully used in the treatment of SCC, as well as in other human cancers with EGFR overexpression, such as colorectal cancer." (PMID 38673914, 2024).
cancer (continued). "By contrast, suppression of integrin signalling inhibits the invasion of epithelial cells as cell to ECM adhesion favours EGFR-dependent cancer proliferation." (PMID 38926351, 2024). "MTOR is a canonical regulator of S6K1 for protein synthesis and translation, and MTOR has been shown to be involved in EGFR-TKI resistance in various cancer types." (PMID 38397056, 2024). "Mobocertinib exhibits its therapeutic activity by selectively inhibiting the EGFR Exon 20 insertions, thereby obstructing aberrant signaling pathways that promote cancer cell proliferation." (PMID 38611728, 2024). "Exploring an inhibitor option, EGCG can function as a tyrosine kinase inhibitor towards activated EGFR in cancer cells by regulating the phosphorylation of EGFR." (PMID 38275516, 2024). "One of a four-membered family of transmembrane receptors, the EGF receptor (also known as ErbB1, HER1, or EGFR) is commonly overexpressed in cancer cells and is associated with a bad prognosis, just as HER2." (PMID 39512829, 2024). "We also suggest that at least one mechanism triggering these changes involves the EV-mediated transmission of EGFR/EGFRvIII from cancer cells to endothelium and prolonged ectopic activation of this oncogenic receptor in these cells." (PMID 38570528, 2024). "On the other hand, similar to TRIB2, TRIB3 binds to EGFR and stabilizes its recycling, facilitating the development of cancer." (PMID 38731938, 2024). "We next measured the ability of EGFR to recruit adapters in EML4-ALK+ cancer cells through co-immunoprecipitation with endogenous EGFR." (PMID 39488530, 2024). "We investigated the effects of Leucine zipper downregulated in cancer-1 (LDOC1) on EGFR CMI and NSCLC treatment." (PMID 38338651, 2024). "GAS6 upregulation or AXL overexpression is often found in cancers with resistance to EGFR-targeted therapy and enhanced survival." (PMID 38892166, 2024). "GE11 peptide (amino acid sequence: YHWYGYTPQNVI) The GE11 peptide, identified through phage display peptide library screening, specifically binds to the epidermal growth factor receptor (EGFR), which is overexpressed in various human cancers." (PMID 39204374, 2024). "We conducted a retrospective observational study of the data of EGFR‐positive NSCLC patients with PR who had undergone surgery at the Shizuoka Cancer Center between October 2002 and November 2017." (PMID 39245880, 2024). "Increased EGFR recycling is predicted to prolong signaling and plays a key role in cancer development." (PMID 39443476, 2024). "As a result, EGF and its receptor (EGFR) are targets for cancer therapies, with several EGFR inhibitors having been developed to block the proliferative signals in cancer cells." (PMID 39064802, 2024). "Upon irradiation, this combination has demonstrated the ability to destroy cancer cells expressing EGFR and generate an immune response." (PMID 38256096, 2024). "This analysis explores the binding affinities of these ligands against key proteins involved in cancer pathways: Epidermal growth factor receptor (EGFR, PDB ID: 1XKK), aromatase (PDB ID: 3S7S), and Phosphoinositide 3-kinase alpha (PI3K alpha, PDB ID: 7PG6)." (PMID 40066125, 2024). "The bone matrix and its interactions with metastatic cancer cells can create a protective niche that allows cancer cells to evade the effects of EGFR-TKIs." (PMID 39108772, 2024). "The epidermal growth factor receptor (EGFR) plays a pivotal role in cancer therapeutics, with small-molecule EGFR inhibitors emerging as significant agents in combating this disease." (PMID 38611728, 2024). "Accordingly, emerging evidence supports that the ABC transporter superfamily can be off-targets of EGFR inhibitors in cancer." (PMID 39033209, 2024). "Several quinazoline-containing compounds were developed with EGFR inhibitory properties and approved against different types of cancers." (PMID 39065774, 2024).
cancer (continued). "An array of cancers harboring oncogenic alterations of PIK3CA, KRAS, PTEN, EGFR, and RHOA have been reported to be associated with activated PI3K/AKT-mTOR signaling." (PMID 39164472, 2024). "Unique pathways induced by the CRP PEV treatment included the HIF-1 signaling pathway, central carbon metabolism in cancer, EGFR tyrosine kinase inhibitor resistance and relaxin signaling pathway." (PMID 39695652, 2024). "Epidermal growth factor receptor-tyrosine kinase inhibitor (EGFR-TKI) has demonstrated efficacy in cancer treatment." (PMID 38980474, 2024). "EGFR signalling is known to activate multiple downstream signalling pathways involved in cancer cell survival, proliferation and migration." (PMID 38762624, 2024). "Aberrant activation of the EGFR/MAPK/mTOR/AKT/ERK1/2 signaling pathway occurs in a variety of human cancer cells." (PMID 38762741, 2024). "Next, an online Kaplan-Meier plot was used to assess the predictive value of the PTGS2/ESR2/EGFR/JUN/MMP2 genes’ signature expression level on OS in numerous human cancers." (PMID 39707884, 2024). "Oleuropein and HT emerge as transformative agents capable of degrading EGFR in several cancer cell lines, as well as quercetin, apigenin, EGCG, and resveratrol." (PMID 38169656, 2024). "The cancer NGS panels include a few hundred cancer-associated genes and mutations with proven clinical importance, such as K-RAS G12V and EGFR L858R, can be targeted by a matching specific inhibitor (i.e., a small molecule or engineered antibody)." (PMID 39715885, 2024). "Consistently, by examining the co‐dependencies of TBC1D31 in the genome‐wide shRNA screening database of 600 cancer cell lines, we found significant enrichment of “Internalization of ErbB1 (EGFR)” by dependent genes." (PMID 39206796, 2024). "The resulting multivalent Rha‐7D12 conjugates were used to investigate the structure‐activity relationship in terms of recruiting endogenous anti‐Rha antibody capability and eliciting Fc effector functions against EGFR‐positive cancer cells." (PMID 38286668, 2024). "Within large spheroids, TAMs displaying M2-polarization markers (including CD163, CD206 and arginase 1) are located in the center of spheroids and surrounded by EGFR+ cancer cells." (PMID 39513610, 2024). "We also conducted a western blot analysis of IL32 expression in PCs derived from three different EGFR‐mutated NSCLC patients, as compared to cancer cell lines, confirming the up‐regulation of IL32 in all PCs." (PMID 39435643, 2024). "This intracellular protein kinase activation protects EGFR-positive cancer cells against EGFR inhibitors targeting the ectodomain." (PMID 38534215, 2024). "EGFR inhibitors have revolutionized cancer treatment, offering substantial benefits in managing various malignancies." (PMID 39130636, 2024). "MS39 (HCC827 cells: DC50 = 5 nM; H3255 cells: DC50 = 3.3 nM) and MS154 (HCC827 cells: DC50 = 11 nM; H3255 cells: DC50 = 25 nM) effectively induced the degradation of mutant EGFR in cancer cells." (PMID 38389844, 2024). "The complex interplay among the epidermal growth factor receptor (EGFR) and hepatocyte growth factor receptor (HGFR/MET) resulted in dysregulation and was associated with cancer pathogenesis and therapeutic resistance." (PMID 39619995, 2024). "About three quarters of the patients had any cancer treatment prior to EGFR inhibitor therapy; in 45.9% of the patients, there was chemotherapy before." (PMID 39693368, 2024). "The EGFR gene is important in cancer because it plays a role in many of the key processes that drive cancer development and progression, including cell growth, division, survival, and migration." (PMID 39453005, 2024). "Research shows that combining HDAC inhibitors (HDACis) with cancer treatments, such as EGFR-TKI, has proven more effective in several settings." (PMID 38927911, 2024).
cancer (continued). "For example, Pedersen and colleagues generated bispecific nanobodies binding properdin and the validated cancer antigen EGFR, and showed that these bispecific molecules were able to activate complement on EGFR-expressing cancer cells." (PMID 38817607, 2024). "Among the top five factors secreted by CAFs in lung cancer, FST surprisingly emerged as a critical player in rescuing cancer cells from EGFR-TKI-induced toxicity, and thus represents a potential target to combat drug resistance in NSCLC." (PMID 38392348, 2024). "For example, the ligand EGF in cancer epithelial cells is significantly associated with the receptors ERBB2 (P value = 0.009) and EGFR (P value = 0) in CAFs, suggesting a potential signaling cascade from the former to the latter." (PMID 38279156, 2024). "TSPAN1, a tetraspanin family member, modulates cell surface protein trafficking and signaling, contributing to cancer cell proliferation and chemoresistance through pathways such as EGFR and integrin-mediated signaling." (PMID 39850570, 2024). "Combination of such two inhibitors has also been investigated in phase II clinical trial (NCT03392246) in EGFR mutant NSCLC cancer, and preliminary signal of activity were seen in phase I trial in a subgroup of patient, negative for MET expression." (PMID 38177190, 2024). "Because of its dysregulation in many cancers, EGFR has been used as a target with mixed success pointing to the need for alternative approaches." (PMID 39357822, 2024). "We found that composite mutations occur in 5% of cancer patients, mostly affecting the PIK3CA, EGFR, BRAF, and KRAS genes, which are common precision medicine targets." (PMID 38757376, 2024). "Overall, the findings highlight direct crosstalk between cancer cells and pericytes, impacting TKI sensitivity via IL32‐β5‐integrin paracrine signaling, proposing an enhanced therapeutic approach for EGFR‐mutated patients." (PMID 39435643, 2024). "EGFR signaling is crucial in promoting the progression of various cancers, including OSCC, where it drives cell proliferation, apoptosis inhibition, chemoresistance, adhesion, and migration." (PMID 39511483, 2024). "The potential of combining statins with other anti-cancer therapies has also been explored, and statins have been found to be effective in overcoming resistance to epidermal growth factor receptor-tyrosine kinase inhibitors (EGFR-TKIs)." (PMID 39308527, 2024). "In conclusion, these observations suggest that E3 ligases and DUBs regulate EGFR signaling, opening new avenues for targeted therapeutic strategies against cancer cell proliferation." (PMID 39048965, 2024). "Pathway analysis revealed enrichment in cancer-related pathways, notably EGFR downstream signaling and IGF1R signaling." (PMID 38542291, 2024). "To manipulate EGFR signaling, we used the cancer therapy drug erlotinib hydrochloride, an inhibitor of EGFR-associated tyrosine kinase." (PMID 39187547, 2024). "The analysis of 11 biomarkers associated with well-known cancer signaling pathways revealed that CDKN2A was characterized by the lowest abundance, while EGFR exhibited the highest expression." (PMID 38956740, 2024). "EGFR has been recognized as a notable therapeutic target for several types of cancers, particularly carcinomas." (PMID 39050443, 2024). "We will administer our vaccine to murine models using high-scoring EGFR EHLA pairs from each cancer." (PMID 38675381, 2024). "We explored the literature using a systematic Pubmed search to identify the current state of the art of specific drug combinations targeting HER2 and EGFR in HER2-positive cancers." (PMID 39684551, 2024). "It blocks cancer cell proliferation and cell cycle and inhibits downstream EGFR signal transduction." (PMID 38338677, 2024). "EGFR signaling is among the most critical pathways in cancers, which promotes proliferation, cell cycle progression, invasion and metastasis." (PMID 38542474, 2024).
cancer (continued). "In NSCLC cells with EGFR activating mutations, blockade of EGFR signaling accelerates MCL-1 degradation and triggers cancer cell apoptosis." (PMID 39543744, 2024). "For example, the EGF and EGFR genes are important for cancer cell proliferation and spread in the body." (PMID 38811597, 2024). "Meanwhile, the genetic variation in a receptor tyrosine kinase, namely epidermal growth factor receptor (EGFR), whose overexpression was linked with cancer progression, is well defined in correlation with its inhibitors." (PMID 39273318, 2024). "Epidermal growth factor receptor (EGFR) is a protein that, when overexpressed or mutated, can play a significant role in the development and progression of various cancers." (PMID 39459468, 2024). "To investigate the possibility of cancer-promoting gene mutations in GC MDR, PCR amplification and Sanger sequencing were performed on all exons of CGA, GATA2, and EGFR in the cell lines we used." (PMID 38960034, 2024). "As the molecular understanding of cancers has improved, several therapies targeting EGFR in cancers have been developed." (PMID 39273661, 2024). "Considering Dsg2 and Dsc2 affected EGFR signaling pathway in some cancers such as cancers of gallbladder, colon, cervix and the lungs, we focused on EGFR phosphorylation and its major downstream AKT and ERK pathways." (PMID 38671389, 2024). "While EGFR is present on human macrophages, its role in macrophages has mainly been studied in cancer research." (PMID 38434401, 2024). "EGFR (epidermal growth factor receptor) and ERBB3 (also known as HER3) are receptor tyrosine kinases that have been implicated in the development of cancer." (PMID 39330508, 2024). "The critical role of the EGFR in cancer development was discovered in the 1960s by Stanley Cohen, who established a link between elevated EGFR levels and malignancy." (PMID 39337496, 2024). "It appears to modulate the expression of epidermal growth factor receptors (EGFR) in cancer cells, potentially inducing resistance to endocrine therapies in estrogen receptor (ER)+ BC patients." (PMID 39273251, 2024). "The anti-EGFR-MPB nanocomposite, designed to specifically target EGFRs on cancer cells, was synthesized and coupled with an anti-EGFR antibody." (PMID 39525484, 2024). "NSCLC consists of a group of different diseases that can present a mutation of epidermal growth factor receptor (EGFR), an oncogenic driver, which can be used as a target for developing new drugs for cancer-targeted treatment." (PMID 38391832, 2024). "Previous research highlighted the impact of domain order on the function of humanized bispecific diabodies targeting EGFR on cancer cells and CD3 on T cells, noting potential steric hindrance." (PMID 39664377, 2024). "Earlier studies have also shown that in cancer cells angiogenesis is often activated through the epidermal growth factor receptor (EGFR) signaling pathway." (PMID 38158791, 2024). "EGFR has emerged as a prime therapeutic target due to its pivotal role in driving uncontrolled cell growth and survival across numerous cancer types." (PMID 39463483, 2024). "The most effective in vitro anti-cancer assay derivatives (4c, 4d, 4e, 4g, and 4h) were tested for EGFR and BRAFV600E inhibition as potential targets for antiproliferative action." (PMID 38257358, 2024). "Some informative studies report the efficacy of EGFR-targeted therapies on cancer progression using EGFR tyrosine kinase kinase inhibitors (TKIs) or antibodies that neutralize EGFR." (PMID 39518052, 2024). "Although some EGFR inhibitors (known as tyrosine kinase inhibitors, TKIs), such as gefitinib, were developed for cancer treatment in HCC, their clinical outcomes are unsatisfactory." (PMID 38693111, 2024). "Therapeutic approaches, such as anti-EGFR antibodies and EGFR tyrosine kinase inhibitors, have been developed and have shown effectiveness in treating some patients with cancer." (PMID 39511483, 2024).